PPP2R2A (protein phosphatase 2 regulatory subunit Balpha)
Diseases named in the same sentence as PPP2R2A in open-access papers (continued):
Sharing a sentence is not in itself a finding about the gene and the disease.
tumor (continued). "Currently, the PP2A holoenzyme complex and certain subunits including PPP2R2A (B55α) are thought to be tumor suppressors in many cancer types." (PMID 25879784, 2015). "Therefore, the impact of B55α low expression/PPP2R2A deficiency varies among different cancer types and the anti-tumor drugs used." (PMID 39659585, 2024). "In addition, PPP2R2A has been proven to be a tumor inhibitor involved in the proliferation, invasion, and epithelial-to-mesenchymal transition (EMT) of cancer cells, including gastric cancer, liver cancer, and ovarian cancer." (PMID 38734666, 2024). "Furthermore, this notable decrease of tumor growth correlated with prolonged overall survival, particularly in animals with tumors originating from PPP2R2A-depleted cells treated with CHK1 inhibition." (PMID 39659585, 2024). "Likewise, there was an increased expression of the death-associated protein kinase 1 (DAPK1) and decreased expression of serine/threonine-protein phosphatase 2A (PPP2R2A) in tumor tissues." (PMID 34305611, 2021). "Another in vivo study found that tumor-secreted exosomal miR-222 can stimulate AKT by constraining protein phosphatase 2 regulatory subunit Balpha (PPP2R2A) expression, and thus inducing p27 phosphorylation and cytoplasmic p27 expression to promote invasion, metastasis and survival." (PMID 31487880, 2019). "However, miR-665 can activate the AKT/mTOR signaling pathway and promote tumor cell proliferation and anti-apoptosis activity by downregulating PPP2R2A (phosphatase 2A subunit B alpha isoform), a phosphatase subunit involved in the negative regulation of multiple signaling pathways." (PMID 37894282, 2023). "In addition, the gene encoding the Protein phosphatase 2A subunit (PPP2R2A), a candidate tumor suppressor that negatively regulates ATM-CHK2, was negatively selected." (PMID 33788831, 2021). "Of note, PPP2R2A homozygous loss is less common (5%) and not increased at later tumor stages." (PMID 31822657, 2019). "In addition, the PPP2R2A was known as an upstream negative effector of Akt/mTOR pathway, suggesting down-regulation of PPP2R2A could impair tumor chemosensitivity." (PMID 31221814, 2019). "Thus, we provide additional clinicopathological support for the role of PPP2R2A (B55α) as a tumor suppressor in BC and present pilot evidence that the PPP2R2A-/low/Cyclin D1high phenotype may be clinically relevant in BC and should be further investigated." (PMID 25879784, 2015). "These core genes contained at least 8 (PPP2R2A, CXCL10, CXCL11, GBP1, IRF1, RARRES3, STAT1, and TAP1) previously identified regulators of tumor progression and distant metastasis." (PMID 38545852, 2024). "The levels of PPP2R2A, PPP2R2B, and PPP2R2D genes expression in tumor tissues of HCC patients from the GEO (GSE76427) and TCGA-LIHC dataset were lower than those in peritumor tissues." (PMID 37554285, 2023). "PPP2R2A D197 and N181 are essential for PPP2R2A-Chk1 signaling and VPA-mediated bidirectional effect on augmenting HU-induced tumor cell death and protecting normal cells." (PMID 36781846, 2023). "MiR-222 directly targets the 3′-UTR of PPP2R2A, which expresses the Protein Phosphatase 2 Regulatory Subunit B Alpha (PPP2R2A), a tumor suppressor, altering the Akt signaling pathway, and therefore enhancing the tumor metastasis in nude mice." (PMID 35186709, 2021). "In the same way, in other tumor models, miR-31 represses the regulatory subunit B alpha isoform of the tumor suppressor PP2A (PPP2R2A)." (PMID 27271609, 2016). "Through repressing tumor suppressors, LATS2 and PPP2R2A, miR-31 promotes cancer growth." (PMID 40332376, 2025). "These miRNA target several tumor suppressor genes, including PDCD4 and PPP2R2A." (PMID 41228448, 2025). "Importantly, we uncovered that PPP2R2A regulates cell cycle progression, cell survival and VPA-mediated bidirectional response to HU treatment through PPP2R2A D197 and N181 in both tumor and normal cells." (PMID 36781846, 2023).
tumor (continued). "Importantly, we found that PPP2R2A D197 and N181 amino acids are essential for the observed VPA-bidirectional effects on tumor and normal cells by regulating Chk1 dephosphorylation at Ser317 and Ser345, cell cycle control and cell survival in response to HU treatment." (PMID 36781846, 2023). "Thus, in luminal-like BC, the PPP2R2A-/low/Cyclin D1high phenotype is significantly associated with worse DFS, independent of HER2 status, tumor size and lymph node status." (PMID 25879784, 2015).
cancer (32 papers, 2014 to 2025). A tumor composed of atypical neoplastic, often pleomorphic cells that invade other tissues. "More importantly, the implications of PPP2R2A deficiency extend beyond a specific cancer type, suggesting a potential broad applicability of DDR inhibitors in treating diverse malignancies with this genetic alteration." (PMID 39659585, 2024). "The current study of PPP2R2A deficiency in the context of cancer therapy, particularly in relation to DDR inhibitors, reveals a promising avenue for targeted treatment." (PMID 39659585, 2024). "Additionally, low expression of PPP2R2A is linked to poor prognosis in multiple cancer types, including HGSOC." (PMID 39659585, 2024). "Given the complexity of PP2A B55α function in different types of cancer, here we sought to identify whether PPP2R2A deficiency enhances the sensitivity of HGSOC to CHK1 inhibition." (PMID 39659585, 2024). "Thus, despite the complexity of PPP2R2A deficiency in the regulation of oncogenic signaling and cancer therapy in the different types of cancer, its impact on the increased sensitivity to CHK1 inhibition in NSCLC and HGSOC appears to be similar." (PMID 39659585, 2024). "Deregulation of PPP2R2A has been implicated in many cancers." (PMID 35227895, 2022). "In addition, PPP2R1A and PPP2R2A alterations have been associated with whole genome doubling in a pan-cancer study of TCGA data." (PMID 28039471, 2017). "Deletions and mutations of PPP2R2A, the gene that encodes PP2A B55α, a protein involved in numerous human cancer types, including breast, prostate, primary plasma leukemia, acute myeloid leukemia and ovarian cell carcinoma, has been observed." (PMID 39659585, 2024). "In summary, in various types of cancer cell lines, including NSCLC and HGSOC cells, PPP2R2A-low expressing/deficient cells exhibit a heightened sensitivity to CHK1i treatment, though with a different means of control of c-Myc expression." (PMID 39659585, 2024). "In contrast, PPP2R2A was the most deleted gene found in > 20% of samples across 17 cancers, followed by the deletion of SLC2A4 in 16 cancers and five additional genes (FOXO3, PPP2CB, PPP2R2D, PPP2R5C and PPP2R5E) in 15 cancer types." (PMID 32807122, 2020). "PPP2R2A is a major regulatory subunit of PP2A, with PPP2R2A promoting cancer cell survival and proliferation." (PMID 33375613, 2020). "Among them, a few have been previously implicated in modulating drug sensitivity in other cancer types, including PPP2R2B, PPP2R2A, PPP2R5A, and PPP2R1A24,31,37." (PMID 33208750, 2020). "We further confirmed that miR-221 directly targeted PPP2R2A in OS cells using western blot and dual-luciferase assays, suggesting miR-221 inhibition to be a potential strategy in developing anti-cancer agents." (PMID 31221814, 2019). "The prevalence of carcinomas with PPP2R2A (B55α) -/low expression was similar in both cohorts, with 51.8% (n = 145) and 54.0% (n = 204) of tumors expressing PPP2R2A (B55α) in the discovery and validation cohorts, respectively." (PMID 25879784, 2015). "Of these, seven genes (BRIP1, ERCC4, FANCD2, FANCG, FANCI, MAD2L2, PPP2R2A) were previously related to the platinum sensitivity/resistance of different types of cancer cells, with NPEPPS being reported for the first time as a platinum drug sensitivity regulator." (PMID 35209078, 2022). "After uptake by poorly invasive PC cells, EV miR-222 is released to further induce downregulation, phosphorylation, and nuclear exit of p27 via the PPP2R2A (protein phosphatase 2 regulatory subunit B alpha)/Akt axis, which ultimately promotes cancer cell proliferation and invasion." (PMID 34205944, 2021). "However, the expression status of the PP2A holoenzyme complex subunits, specifically PPP2R2A, as a biomarker has hardly been explored in any cancer type, including BC." (PMID 25879784, 2015).
cancer (continued). "Based on the functional characteristics and cancer-specific expression pattern of PPP2R2A (B55α) and Cyclin D1, it is evident that both PPP2R2A and the PPP2R2A-/low/Cyclin D1high phenotype deserve further attention to better uncover their possible clinical and biological importance in BC." (PMID 25879784, 2015). "PPP2R2A (B55α)-/low carcinomas have significantly shorter DFS and OS." (PMID 25879784, 2015). "This may be particularly potent in cancers with PPP2R2A deletions." (PMID 33788831, 2021). "Also, WDR82 was predicted to interact with PPP2R2A; while PPP2R2A was reported to mediate inhibition of ERK and Akt pathways in cancer." (PMID 33282547, 2020). "PPP2R2A, which codes for the α isoform of the regulatory B55 subfamily of PP2A, is involved in the negative control of cancer cell growth and development." (PMID 31221814, 2019).
infection (3 papers, 2013 to 2014). The state of being infected such as from the introduction of a foreign agent such as serum, vaccine, antigenic substance or organism. "When PPP2R2A- and CENPE -depleted cells were infected with HPV16-GFP, infection was increased, which supported the notion that the length of NE absence may be a kinetic bottleneck for import of the vDNA during mitosis." (PMID 24874089, 2014).
PPP2R2A also shares sentences with these, for which no sentence is quoted: colorectal cancer (3 papers); liver cancer (2); multiple myeloma (2); triple-negative breast carcinoma (2); acute T cell leukemia (1); adenocarcinoma (1); adenovirus infection (1); Alzheimer disease (1); cervical cancer (1); COVID-19 (1); diffuse large B-cell lymphoma (1); Fanconi anemia (1); head and neck carcinoma (1); influenza (1); Insulin resistance (1); leiomyoma (1); lung diseases (1); metastatic melanoma (1); neurodegenerative disease (1); osteoporosis (1); ovarian tumor (1); pancreatic ductal adenocarcinoma (1); plasma cell leukemia (1); preeclampsia (1); prostate (1); pulmonary fibrosis (1); serous ovarian cancer (1); squamous cell carcinoma (1).